STAT3 (signal transducer and activator of transcription 3)
Diseases named in the same sentence as STAT3 in open-access papers (continued):
Sharing a sentence is not in itself a finding about the gene and the disease.
colon carcinoma (continued). "Colon cancer cells stimulate macrophages to produce IL-6, which activates STAT3 in tumor cells." (PMID 28725043, 2017). "In addition, IL-6 was found to induce STAT3 phosphorylation in RAB3C-overexpressing colon cancer cells, thus promoting migration." (PMID 28784136, 2017). "Importantly, induction of IL-6 / STAT3 axis was also detected in colonic tumors derived from Sdc1 KO mice." (PMID 28350804, 2017). "In colonic tumors, lack of vanin-1 is associated to higher levels of PPARg and to a reduction in IL-6 production and STAT3 activation." (PMID 28448444, 2017). "Furthermore, we demonstrated that blockade of persistent STAT3 signaling inhibited proliferation, cell migration and colony formation, as well as induced apoptosis in liver and colon cancer cells." (PMID 26883202, 2016). "Our results suggest that LY5 is a potent STAT3 inhibitor and may be a potential drug candidate for liver and colon cancer therapy." (PMID 26883202, 2016). "The activation of Stat3 and Stat5 has been shown to promote cell proliferation and invasion in cancer, while Stat3 was also found to be persistently activated and overexpressed in colon cancers." (PMID 27092172, 2016). "Our results suggest that inhibition of IL-6 may enhance chemosensitivity of colon cancers with overactive STAT3 to platinum agents." (PMID 27006530, 2016). "Furthermore, LY5 inhibited STAT3 phosphorylation and suppressed colon tumor growth in a mouse model in vivo." (PMID 26883202, 2016). "STAT3 can induce EMT of colon cancer cells, activate ZEB1 and suppress E-cadherin." (PMID 26824417, 2016). "Furthermore, STAT3 inhibition can promote apoptosis of human pancreatic and colon cancer cells in vitro and in vivo." (PMID 25961376, 2015). "Interestingly, the reduced levels of IL-6 mRNA observed in the PDXs upon p38 MAPK inhibition correlated with reduced phosphorylation of STAT3, an important regulator of colon tumor cell proliferation and survival." (PMID 25890501, 2015). "We therefore evaluated whether STAT3 activity plays a role in HES1’s regulation of MMP14 in colon cancer cells." (PMID 26650241, 2015). "Constitutively activated STAT3 has been identified in many cancers including colon cancer." (PMID 26474284, 2015). "Thus, it is possible that (E)-4-(3-(3,5-dimethoxyphenyl)allyl)-2-methoxyphenol inhibits colon cancer cell growth via inhibition of both STAT3 and NF-κB pathways." (PMID 26474284, 2015). "Activation of STAT3 is also a marker of poor prognosis in human colon cancer." (PMID 25961376, 2015). "Moreover, there is evidence that IL-6 and STAT3 signalling are important for the proliferation of tumour cells in mouse colon cancer models." (PMID 26079427, 2015). "Knock down of STAT3 or NF-κB p50 subunit by STAT3 small interfering RNA (siRNA) or p50 siRNA magnified (E)-4-(3-(3,5-dimethoxyphenyl)allyl)-2-methoxyphenol-induced inhibitory effect on colon cancer cell growth." (PMID 26474284, 2015). "IL-6 induced a STAT3-mediated IL-10 production in colon tumor cells is also reported." (PMID 26556872, 2015). "Ursolic acid inhibits the growth of colon cancer-initiating cells by inhibition of STAT3." (PMID 26474284, 2015). "STAT3 has been shown to be constitutively activated or overexpressed in colon cancers." (PMID 24743778, 2014). "Moreover, recent work documented that activation of STAT1 and STAT3 correlated with a better prognosis for colon cancer patients." (PMID 24833526, 2014). "Increased intratumoral IL-6 and possibly IL-11 expression suggested that dietary iron may promote colonic tumor development via a Stat3-mediated pathway." (PMID 24223168, 2013). "STAT3 activation can induce EMT by targeting E-cadherin in colon cancer." (PMID 24376686, 2013).
colon carcinoma (continued). "Increased intratumoral IL-6 and possibly IL-11 expression suggested that Stat3 activation may contribute to the development of dietary iron induced-colonic tumors." (PMID 24223168, 2013). "IL-6 has been shown to lead to STAT3 activation in colon cancer." (PMID 24098947, 2013). "It still remains unclear whether STAT3 plays a role in bufalin-induced apoptosis in cancer cells, especially colon cancer cells." (PMID 23110625, 2012). "To date, whether STAT3 is activated and the effects of STAT3 inhibition by a newly developed curcumin analogue, GO-Y030, in colon cancer stem cells are still unknown." (PMID 21694723, 2011). "In epithelial cells, Stat3 also induces other proteins that indirectly suppress apoptosis, including the chaperone protein Hsp70 and the C-type lectin-type RegIIIβ, which are both overexpressed in human colon cancer and inflammatory bowel disease." (PMID 20478049, 2010). "Additionally, STAT3 knockdown using RNA interference in colon cancer cell lines reduced survivin expression resulting in anoikis." (PMID 19284568, 2009). "Also, previous research reported that miR-181b also serves as a direct regulator of PIAS3, and its overexpression could downregulate PIAS3, leading to STAT3 activation through phosphorylation in positive feedback in colon cancer cells." (PMID 38185635, 2024). "Moreover, the tested flavonoids inhibit the STAT3/NF-κB pathway in HCT-116 colon carcinoma cells." (PMID 36836951, 2023). "Finally, it was revealed that E2F3 affected the STAT3 pathway to modulate stemness in colon cancer." (PMID 37456248, 2023). "In summary, research of this study indicates that apigenin may have potential anticancer effects against colon cancer by: Inducing apoptosis and autophagy; Targeting specific signaling pathways such as STAT3 and NF‐B/Snail; Inhibiting EMT, migration, and invasion of colon cancer cells." (PMID 37970406, 2023). "Thus, NOSTRIN-mediated decrease in STAT3 expression could be just another step towards reduced colon cancer aggressiveness." (PMID 35642021, 2022). "Furthermore, the co-immunoprecipitation assay confirmed that GOLPH3 interacted with p-STAT3 (Tyr705) and total STAT3 in colon cancer cells, which indicates that GOLPH3 might act as a transport protein." (PMID 35372504, 2022). "In addition, we also provided the first evidence that ZNF460 promoted the invasion and metastasis of colon cancer cells through activating the JAK2/STAT3 signaling pathway and might be a novel therapeutic target in colon cancer." (PMID 33976729, 2021). "Our data show that the AOM/DSS-induced increases in β-catenin signaling and the phosphorylated form of STAT3 were effectively inhibited by BL, suggesting that the beneficial effects of BL against colon cancer development may partially depend on the inhibition of STAT3/β-catenin signaling." (PMID 34684488, 2021). "Therefore, G-749 may contribute to tumor growth inhibition by not only inhibiting the phosphorylation of AKT and STAT3 in colon cancer, but also by generating soluble ICD." (PMID 34721022, 2021). "JAK/STAT3 signal transduction has the ability to suppress tumor immunity, and the application of JAK inhibitors in colon cancer can suppress sporadic colon cancer caused by mutations in APC inhibitory genes, and it may also provide treatment opportunities for other oncogenes with resistance." (PMID 33117713, 2020). "Therefore, we investigated whether ATP-mediated P2 × 7 receptor activation has an effect on STAT3 signaling in colon cancer cells." (PMID 33330466, 2020). "In addition, we examined the effects of this treatment on the IL-6-mediated activity of HCT116 human colon cancer cells, including cell proliferation and apoptosis, STAT3 phosphorylation levels and transcriptional activity, and the multiple target genes of the IL-6/STAT3 signalling pathway." (PMID 33082817, 2020).
colon carcinoma (continued). "In addition, reactive oxygen species could induce CD80 expression via the JNK and p38 MAPK pathways, that activated STAT3 transcription factor in colon cancer epithelial cells." (PMID 31072360, 2019). "Other studies have clarified the presence of cytokine (IL-6 and IL-22)-responsive elements in the promoter regions of REG Iα and Iβ and HIP/PAP in pancreatic or colon cancer cells, although it remained unclear whether STAT3 and/or other transcriptional factors actually bind to these elements." (PMID 31780871, 2019). "Hence, we sought out to test if JAKs were involved in the activation of STAT3 in MCS of colon cancer cells and whether JAK-inhibition can affect induction of IRF9 and the panel of IRDS genes." (PMID 30679726, 2019). "Since activated STAT3 and IL-11 were found to be overexpressed and promote tumorigenesis in most colon cancers, we hypothesized a potential inhibitory role of bazedoxifene in colon cancers." (PMID 30736824, 2019). "Importantly, increased activation of STAT3 was also demonstrated in AOM-DSS induced colonic tumors derived from Sdc1-KO, as compared to wt mice, as evidenced by a statistically significant increase (p = 0.004) in the number of cells positive for nuclear-localized pSTAT3." (PMID 28350804, 2017). "Therefore, we used shRNA to suppress STAT3 expression of in the HT-29 colon cancer cell line." (PMID 28725043, 2017). "However, the role of STAT3 in colon cancer stem cells and the effect of STAT3 inhibition in colon cancer stem cells are still unknown." (PMID 21694723, 2011). "In a colitis-induced colon cancer model, triptolide further suppresses IL-6 secretion and reduces the expression of IL-6 receptor (IL-6R), JAK1, and phosphorylated STAT3 proteins." (PMID 40490812, 2025). "IL11 has not been previously associated with AHR but is known to suppress CD4+T cells mediated anti-tumor immunity, and the IL11/STAT3 inhibition increased MHC-I expression and T cell infiltration in colon cancers." (PMID 40283908, 2025). "Elevated expression of IL‐6 and activation of the JAK2/STAT3 pathway are tightly correlated with the progression of malignancies, including HCC, colon cancer, bc, NSCLC, and NPC." (PMID 41316520, 2025). "EGCG also disrupts the STAT3/CXCL8 signaling pathway, thereby inhibiting the formation of NETs and reducing motility and invasion in colon cancer (SW480) cells." (PMID 40490812, 2025). "Our results indicated IRSp53 upregulation in patients suffering colon cancer and reduction of EGFR/c-Src/IRSp53/p-AKT/p-Stat3/cyclin D1 signaling pathway, which led to suppression of cell proliferation in the hAMSCs-treated HT-29 colon cancerous cells." (PMID 41200137, 2025). "In colon cancer, CXCL8 promotes M2 macrophage polarization by activating the STAT3 signaling pathway and upregulating PD-L1 expression in M2 macrophages while simultaneously reducing T cell infiltration." (PMID 40270974, 2025). "The complex showed remarkable antiproliferative activity against human colon cancer HCT-116 cells and exhibited a concentration-dependent reduction in STAT3 protein expression." (PMID 39697768, 2025). "The MUC2 protein directly mediates Chk2/STAT3/CREB/ATF-1 signaling and E-cadherin expression in colon cancer." (PMID 40859234, 2025). "Colon cancer cells (HT29) treated with apigenin trigger apoptosis by concurrently downregulating Mcl-1 and Bcl-xL by blocking the STAT3 (signal transducer and activator of transcription 3) pathway." (PMID 41155376, 2025). "By reducing the STAT3 expression, EGCG prevents colon cancer cells from proliferating, migrating, and invading." (PMID 39201782, 2024).
colon carcinoma (continued). "In our investigation using the AOM/DSS colon cancer model, we explored the interplay between PXR and the IL‐6/STAT3 pathway." (PMID 39495702, 2024). "A significant highlight of this work is our innovative use of GENET to discover and validate a new pathway in colon cancer, specifically, the promotion of IGF2 by WNT4 through the activation of STAT3." (PMID 39373342, 2024). "Kaempferol also induce chemo-sensitization to 5-FU in drug-resistant LS174 colon cancer cells by blocking ROS production and modulating the JAK/STAT3, MAPK, PI3K/AKT, and NF-κB signaling pathways." (PMID 39061884, 2024). "In colon cancer, under hypoxic conditions, CAF-derived IL-6 activates STAT3 signaling to promote tumor progression or induce drug resistance via a HIF-1a/miR-338-5p/IL-6 feedback loop." (PMID 39251966, 2024). "EGCG inhibits NET formation by regulating the STAT3/CXCL8 signaling pathway, which further suppresses the colon cancer cells’ invasion and migration." (PMID 39201782, 2024). "Pearson correlation analysis of transcriptome data from 14 patients with colon cancer indicated strong positive correlations between WNT4 and STAT3, and between STAT3 and IGF2." (PMID 39373342, 2024). "This function is concordant with what has been identified in colon cancer, in which HSP110 interacts with and activates STAT3." (PMID 38773631, 2024). "The investigators have found a correlation between expressional STAT3/STAT5 ratio and prognosis in colon carcinoma." (PMID 36968603, 2023). "In addition, FTGs activated the AMPK/mTOR autophagy pathway and downregulated the expression of JAK2/STAT3 apoptotic pathway proteins, while upregulated the expression of Bax and caspase-3 proteins and downregulated the expression of Bcl-2 proteins to exert an anti-colon cancer role." (PMID 38202610, 2023). "In colon cancer, RBP4 maintains the stemness of colon cancer stem cells by promoting the phosphorylation of STAT3, which affects colon cancer progression." (PMID 37313408, 2023). "It has been reported that STAT3 activity is amplified by HES1 in mouse neuroepithelial cells and colon cancer cells." (PMID 37373457, 2023). "In particular, STAT3 was under-expressed while STAT4 and STAT5 were over-expressed in colon cancer tissue." (PMID 36968603, 2023). "The cytotoxicity of the optimized PLGA NPs was assessed against human colon cancer cell lines, HT-29, through caspase-3, vascular endothelial growth factor (VEGF), and signal transducer and activator of transcription-3 (STAT-3) proteins levels assay." (PMID 36839928, 2023). "A colon cancer-based study reported that formononetin inhibited cell proliferation and invasion via the inhibition of cyclin D1 and MMP-2/9 expression through p-STAT3, p-PI3K, and p-Akt inactivation." (PMID 37298670, 2023). "In colon carcinoma, STAT3 and STAT5 were found abnormally expressed and the STAT3/STAT5 expression ratio was suggested as a potential independent prognostic marker." (PMID 35468892, 2022). "Strikingly, Phd2 haplodeficiency significantly increased STAT3 and ERK1/2 phosphorylation in epithelial cells of AOM/DSS-induced colon tumors." (PMID 36509284, 2022). "Other studies showed that CurE was able to chemo-sensitize colon tumor cells by regulating TFAP4/Wnt/beta-catenin signaling and inhibit the proliferation of pancreatic adenocarcinoma cells by modulating STAT3 signaling." (PMID 36184616, 2022). "It has been reported that STAT3 can interact with HIF1, and that a complex of STAT3 and HIF1 induced PD-L1 expression in colon cancer cells, and in hypoxic NSCLC cells." (PMID 34268602, 2022). "Ab27 suppressed the tumor growth in liver and colon cancer xenograft models, including sorafenib-resistant HCC, and decreased the phosphorylation of FAK, p27Kip1, and STAT3." (PMID 35211652, 2022).
colon carcinoma (continued). "In fact, it has been reported that miRNAs regulate the expression of STAT3 through transcription factors such as NF-κB or HIF-1α, with the latter closely related to hypoxia in cancers such as leukemia or colon cancer." (PMID 35565420, 2022). "Another study found that the expression levels of both STAT3 and NRF2 were increased in HT-29 colon cancer cells, but when treated with the combination of 5-fluorouracil (5-FU) and stattic, the level of NRF2 decreased after the reduction of STAT3 expression." (PMID 36557902, 2022). "Anti-IL-6 neutralizing antibody, JAK2 inhibitor and STAT3 gene knockout in mouse cancer cells reduced BMF and BMF-CM induced colon cancer cell spheroid formation." (PMID 36591515, 2022). "EGCG reduced STAT3 and CXCL8 expression in colon-cancer-patient-derived neutrophils to inhibit the formation of neutrophil extracellular traps and suppress colon cancer migration in vitro." (PMID 36700235, 2022). "In colon cancer, PTK6 interacts with JAK2 and increases STAT3 phosphorylation to enhance stemness and chemoresistance." (PMID 35562900, 2022). "Our study found that loss of GOLPH3 attenuated the IL-6 induced phosphorylation of STAT3 in colon cancer cells, while the overexpression of GOLPH3 enhanced STAT3 phosphorylation in the presence of IL-6." (PMID 35372504, 2022). "PTK6 promotes STAT3 and ERK5 activation to promote cell survival and response to DNA-damaging treatments in colon cancer cells." (PMID 35562900, 2022). "Increased activity of STAT3 induced by EGFR has been found in breast, prostate, lung, head, and neck, pancreatic and colon cancer." (PMID 34741044, 2021). "From a clinical standpoint, high levels of nuclear pRKIP and STAT3 are correlated with poor prognosis in stage II colon cancer patients, suggesting that RKIP regulates STAT3-mediated cell survival." (PMID 34944867, 2021). "Our study showed that EGCG inhibited colon-cancer-cell proliferation and migration in both primary SW480 cells and metastatic SW620 and LS411N cell lines by suppressing the promoter activity of STAT3 and downregulating the transcription of STAT3." (PMID 33747527, 2021). "To further explore the mechanism of ZNF460 in promoting the invasion and metastasis of colon cancer, we found that ZNF460 activated JAK2/STAT3 signaling pathway." (PMID 33976729, 2021). "The colon cancer cells positive for ALDH and CD133 demonstrate activation of STAT3 signaling and its phosphorylation." (PMID 34769099, 2021). "The results of this study indicate that orlistat alleviates colon cancer promotion in WD-driven CAC mice by suppressing inflammation, especially by inhibiting STAT3 and NF-κB activation." (PMID 34440829, 2021). "Gal2 overexpression decreased the proliferation of human colon tumor epithelial cells and blunted H2O2-induced STAT3 phosphorylation." (PMID 33110234, 2021). "We used the CRISPR-CAS9 gene editing system to delete a short sequence encoding amino acids 400-411 in the DNA-binding domain (amino acid sequence: 317-567) from STAT3 gene in SW480, SW620 and HCT116 colon cancer cells." (PMID 33535185, 2021). "The activation of STAT3 by IL-6 in colon cancer was studied by examining HCT116 cells after IL-6 treatment, and specifically looking at STAT3 and pRKIP levels." (PMID 34944867, 2021). "DHA induced the apoptosis of colon cancer cells by targeting janus kinase 2 (JAK2)/signal transducer and activator of transcription 3 (STAT3) signaling." (PMID 33613116, 2021). "They concluded that PAC exhibits anti-colon cancer properties that have potential, by targeting cyclin D1 and suppressing JAK2/STAT3, AKT/mTOR and MEK/ERK signaling pathways as well as their common downstream effector which is cyclin D125." (PMID 34083581, 2021).